ALB (albumin)
Diseases named in the same sentence as ALB in open-access papers (continued):
Sharing a sentence is not in itself a finding about the gene and the disease.
respiratory failure (106 papers, 2004 to 2026). The significant impairment of gas exchange within the lungs resulting in hypoxia, hypercarbia, or both, to the extent that organ tissue perfusion is severely compromised. "The nomogram developed in this study based on D-dimer, lactate, pro-BNP, albumin, globulin, transcutaneous blood oxygen saturation, and pulmonary infection was found to effectively predict respiratory failure risk in SA-AKI patients within 48 h of admission." (PMID 41140320, 2025). "Prognostic factors, such as age, LDH levels, respiratory failure, malignancy, and low albumin levels, have been reported, and these factors are associated with an increased mortality rate." (PMID 40234819, 2025). "Studies have shown that abnormal ALB levels were associated with decreased respiratory muscle endurance, impaired immune function, and increased risk of CI and respiratory failure." (PMID 39148703, 2024). "Increase in effective circulating blood volume with vasoconstrictors and oncotic pressure with intravenous albumin results in increased intravascular volume, potentially resulting in fluid overload with risk of respiratory failure." (PMID 39132033, 2023). "In 2021, we highlighted an association between in-hospital mortality, respiratory failure (β = 3.1, p = 0.01) and serum albumin (β = −2.8, p = 0.01)." (PMID 37629346, 2023). "In untreated ARDS group, respiratory failure persisted until the end of the experiment probably due to surfactant dysfunction caused by interaction with leaked plasma proteins (albumin and fibrinogen) and/or inflammation." (PMID 36927675, 2023). "The following host factors significantly increased the risk of the composite outcome: albumin < 2.5 g/dL (adjusted OR [aOR]: 1.59; 95% CI 1.29–2.29), respiratory failure (aOR: 1.51; 95% CI 1.20–2.11), and dependent ADL (aOR: 1.46; 95% CI 1.18–2.12)." (PMID 37100850, 2023). "Decreased albumin levels are associated with an increased risk of acute respiratory failure and increased frequency of mechanical ventilation." (PMID 36558522, 2022). "Early symptoms of respiratory failure, a higher respiratory rate, and lower albumin and globulin levels are independently associated with oxygen therapy." (PMID 33481912, 2021). "A lower BMI, respiratory failure, malignancies, and lower albumin levels were also significantly associated with in-hospital mortality." (PMID 33619334, 2021). "High APACHE II score, low CCI, low albumin levels and the requirement for inotropic support were found to be independently risk factors of 30-day mortality in the geriatric patients with respiratory failure in ICU." (PMID 33437244, 2021). "Patients in the non-survivor group were significantly older, had a greater frequency of respiratory failure, loss of consciousness, lower body mass index, hemoglobin, albumin, and ESMcsa/BSA." (PMID 33619334, 2021). "Albumin, a nutritional marker, reflects both respiratory muscle function and plasma oncotic pressure, with lower levels increasing the risk of pulmonary edema and respiratory failure." (PMID 40606461, 2025). "Furthermore, low albumin concentration was reported to be a risk factor for acute respiratory failure and mortality in patients with COPD." (PMID 38674175, 2024). "Independent risk factors for respiratory failure included D-dimer, lactate, pro-BNP, albumin, globulin, transcutaneous blood oxygen saturation, and pulmonary infection." (PMID 41140320, 2025). "We accordingly developed a nomogram to predict the prognosis of patients with KP infection and observed that the factors age, CCI, respiratory failure, SOFA score, and albumin were associated with 30-day mortality." (PMID 39564105, 2024). "A post hoc analysis of the study data showed that respiratory failure events were associated with severity of HRS with serum creatinine levels and injudicious use of intravenous albumin." (PMID 39132033, 2023).
respiratory failure (continued). "Previous studies have shown that patients with respiratory failure have low albumin levels due to severe metabolic depletion." (PMID 36827460, 2023). "A serum albumin level < 2.5 g/dL, respiratory failure, and dependent activities of daily living were independent risk factors for ADRs or death." (PMID 37100850, 2023). "Shock, respiratory failure, albumin, and fibrinogen are potential independent prognostic factors for 60-day mortality." (PMID 35559342, 2022). "Our study provides a new method to assess pulmonary function and judge prognosis, a new strategy to prevent and treat respiratory failure, and a theoretical basis for the supplementation of albumin in patients with poor pulmonary function." (PMID 36262258, 2022). "After adjusting for possible confounding factors, a prognostic model consisting of shock, respiratory failure, albumin, and fibrinogen was established for predicting the outcome of patients with BSI." (PMID 35559342, 2022). "Further, to test the four independent prognostic factors (shock, respiratory failure, albumin, and fibrinogen), we used the log-rank test to make a survival analysis on patients with BSI." (PMID 35559342, 2022). "Since shock, respiratory failure, albumin, and fibrinogen were independent prognostic factors, we further analyzed the predictive value of four indicators and their combination for the prognosis of patients with BSI." (PMID 35559342, 2022). "Lower albumin levels correlated with a higher rate of peripancreatic fluid collection and respiratory failure (p < 0.001 and p = 0.051)." (PMID 34921151, 2021). "Our cohort study also showed that SAE patients with respiratory failure, worse coagulation function, and lower albumin levels were more likely to die." (PMID 34489922, 2021). "Respiratory failure-related symptoms, elevated respiratory rate, low albumin and globulin levels, and fever at admission are independent risk factors related to the requirement of oxygen." (PMID 33481912, 2021). "Male, respiratory failure, malignancies, and a lower albumin level and Barthel Index on admission were also significantly associated with 30-day mortality." (PMID 33619334, 2021). "We should promptly correct the respiratory failure, give component blood transfusions, correct coagulation function, supplement albumin, and reduce the mortality of SAE patients." (PMID 34489922, 2021). "Serum albumin levels and duration of NPPV treatment were independent risk factors for the efficacy of NPPV treatment in respiratory failure." (PMID 34861893, 2021). "Detrimental consequences of NIV due to uncontrolled TV and pressure swings need to be considered when treating patients in hypoxemic respiratory failure with low serum albumin." (PMID 31337440, 2019). "Detrimental consequences of non-invasive ventilation due to uncontrolled tidal volume and pressure swings need to be considered when treating patients in hypoxemic respiratory failure with low serum albumin." (PMID 31337440, 2019). "We examined predictors of the post-stenting mortality, including age, serum albumin, tracheal diameter, smoking, opioid use, respiratory failure, and performance status (PS)." (PMID 28651011, 2017). "On univariate analysis, age, albumin, PS before airway stenting, respiratory failure, admission route, and PS grade were the candidates as possible predictors of prognosis after the procedure." (PMID 28651011, 2017). "Our results are consistent with previous data for HIV-positive patients that mortality was influenced by respiratory failure, high lactate dehydrogenase, low serum albumin, concomitant bacterial infection, and a need for mechanical ventilation." (PMID 28938676, 2017). "Subsequently, free fatty acids dissociate from albumin in the blood, enter the alveolar capillary membrane, and destruct the pulmonary blood microcirculation, leading to respiratory failure." (PMID 25887309, 2015).
respiratory failure (continued). "The prognostic factors of mortality in HIV-infected patients admitted to the ICU are acute illness severity, poor functional status, low albumin rate, and respiratory failure requiring mechanical ventilation." (PMID 25159592, 2014). "Low serum albumin level is closely associated with adverse outcomes and prolonged LOS in multiple diseases, such as acute coronary syndrome, acute heart failure, and respiratory failure." (PMID 41586218, 2025). "Prognostic factors for non-HIV PCP include several factors, such as advanced age, elevated lactate dehydrogenase (LDH) levels, low albumin, respiratory failure, hematological malignancies, increased blood urea nitrogen, concurrent bacteremia, and pre-existing lung disease." (PMID 40234819, 2025). "Low albumin levels can lead to pulmonary edema and respiratory failure." (PMID 41140320, 2025). "In this retrospective study, 10 variables were identified as independent risk factors for respiratory failure after hospital admission in septic patients, namely, respiratory rate, lactic acid, Pro-BNP, D-dimer, albumin, globulin, pulse oxygen saturation, GCS, lung infection, and peritonitis." (PMID 38028763, 2023). "Dependent ADL, extrapulmonary TB and/or extensive disease, respiratory failure, one or more comorbidities, albumin < 2.5 g/dL, and creatinine clearance < 30 mL/min were more common among patients who had ADRs or died within 60 days than among those who did not." (PMID 37100850, 2023). "Interestingly, Spearman analysis revealed that respiratory failure was strongly associated with all blood indices except LYM, GGT, and albumin." (PMID 36747045, 2023). "In conclusion, this study demonstrated that shock, respiratory failure, albumin, and fibrinogen are independent prognostic factors for 60-day mortality, and the appropriate treatment measures should be taken in light of these prognostic factors to improve the survival rate of patients with BSI." (PMID 35559342, 2022). "Additionally, other important variables included respiratory failure, serum calcium, albumin, blood pH, heart rate, and RDW in a descending sequence of importance." (PMID 36325351, 2022). "Patients with respiratory failure had significantly lower median lymphocyte count (0.7*109/l vs. 1.3*109/l, P < 0.0001), median platelet count (155.5*109/l vs. 186.5*109/l, P = 0.0008) and median albumin levels (40.0 vs. 41.9 g/l, P = 0.0005)." (PMID 33468282, 2021). "As these models used hospital-based data, many variables in these models such as respiratory failure requiring oxygen, serum albumin, activity of daily living, dehydration, hypoxemic respiratory failure, orientation disturbance, etc. are not routinely collected by TB programs." (PMID 30611208, 2019). "Risk factors associated with increased mortality rate including old age, female sex, longer time from onset of symptoms to diagnosis, respiratory failure, solid tumors, high lactate dehydrogenase, low serum albumin, bacterial, and aspergillus co-infection, etc (P < 0.05)." (PMID 28938676, 2017). "The clinical characteristics of our population, such as an increased proportion of patients admitted with shock, respiratory failure, higher severity indices and lower albumin levels, may partially explain the higher mortality." (PMID 26090676, 2015). "Furthermore, in terms of XGBoost model, SOFA score had the most influence on in-hospital mortality prediction, followed by anion gap, billirubin, OASIS score, albumin, white blood cell, bicarbonate, length of hospital, acute respiratory failure, RDW, temperature, creatinine, platelet, MCHC and BMI." (PMID 36701342, 2023). "Therefore, serum albumin can be increased to prevent respiratory failure." (PMID 36262258, 2022).
respiratory failure (continued). "Multivariate analysis indicated that albumin (odds ratio [OR] = 0.94, 95% confidence interval [CI]: 0.89–0.99), fibrinogen (OR = 0.61, 95%CI: 0.46–0.82), shock (OR = 16.61, 95%CI: 7.00–39.41), and respiratory failure (OR = 47.53, 95%CI: 19.93–133.64) were independent factors." (PMID 35559342, 2022). "Respiratory failure in animals with ARDS persisted until the end of the experiment probably due to surfactant dysfunction, which could be caused by interaction with leaked plasma proteins (albumin and fibrinogen)." (PMID 34959373, 2021). "Multivariate Cox regression analysis revealed age ≥65 years, higher CCI, presence of respiratory failure, higher SOFA score, albumin ≤30 g/L, and appropriate treatments in 3 days were associated with fatal outcomes." (PMID 39564105, 2024). "A prediction model (LDH-model) integrating LDH, age, gender, ethnicity, potassium, calcium, albumin, hemoglobin, ALP, vasopressor, Elixhauser score, and respiratory failure was established in the training set." (PMID 37807068, 2023). "In this study, we also found that albumin, uric acid, platelet count, white blood cell count, CURB-65 score, and acute respiratory failure were independent factors for AKI in patients with CAP." (PMID 36974657, 2023). "Although respiratory failure due to pulmonary edema was recently reported with the use of vasoconstrictors and albumin, it could not be linked in the current study to the use of any of the studied medications due to the small number of patients that suffered from this adverse event." (PMID 34276366, 2021). "According to our results, SAPS II, renal replacement therapy, temperature, SpO2, albumin, international normalized ratio (INR), lactate, and respiratory failure were independent prognostic factors for SAE patients (p < 0.01 or p < 0.05)." (PMID 34489922, 2021). "A Lasso regression model and multivariate cox regression analysis identified SAPS II, renal replacement therapy, temperature, SpO2, albumin, INR, lactate, and respiratory failure as independent prognostic factors for SAE patients in the training cohort." (PMID 34489922, 2021). "We identified independent factors for the prognosis of SAE patients, which included SAPS II, renal replacement therapy, albumin, INR, lactate, temperature, SpO2, and respiratory failure." (PMID 34489922, 2021). "Multivariate Cox regression analysis identified several factors associated with 30-day mortality, including age ≥65 years, higher CCI, the presence of respiratory failure, higher SOFA score, albumin level ≤30 g/L, and appropriate treatments within the first 3 days." (PMID 39564105, 2024). "Our model showed that nine characteristics, including low albumin, APSIII, chemotherapy, high lactate, low chloride, hepatic metastases, respiratory failure, SAPSIII, and low total protein, were independent predictors of prognosis in patients with secondary bone tumors in the intensive care unit." (PMID 38546896, 2024). "In the non-survivor group, high incidences of respiratory failure and comorbidities were recorded, as well as lower hemoglobin and albumin levels, performance status scores, and ESMcsa/BSA." (PMID 37511715, 2023). "Using advanced machine learning techniques, we could identify some important clinical features associated with in-hospital mortality such as SOFA score, anion gap, albumin, OASIS score and acute respiratory failure." (PMID 36701342, 2023). "Multivariate logistic regression analysis and stepwise regression showed that the respiratory rate, lactic acid, Pro-BNP, D-dimer, albumin, globulin, pulse oxygen saturation, GCS, lung infection, and peritonitis were independent factors related to respiratory failure." (PMID 38028763, 2023). "Results showed that performance status and hemoglobin and albumin levels, but not ESMcsa/BSA and BMI, were significantly associated with in-hospital mortality after adjusting for age, comorbidities, CRP level, and respiratory failure." (PMID 33849637, 2021).
respiratory failure (continued). "The non-survivor group had a high incidence of respiratory failure and comorbidities and lower hemoglobin and albumin levels, performance status score, and ESMcsa/BSA." (PMID 33849637, 2021). "Lasso regression and multivariate Cox regression indicated that factors including respiratory failure, lactate, international normalized ratio (INR), albumin, SpO2, temperature, and renal replacement therapy were significantly correlated with hospital mortality." (PMID 34489922, 2021). "Albumin has a long half-life of approximately 18 days and because of this fact it is unlikely to change with development of acute respiratory failure in patients with COPD." (PMID 15566574, 2004). "The significance of lactate and albumin in acute respiratory failure (ARF) has not been studied." (PMID 40130722, 2025). "Multivariate Cox regression analysis revealed that age ≥65 years, higher CCI scores, higher Sequential Organ Failure Assessment scores, the presence of respiratory failure, albumin levels ≤30 g/L, and non-appropriate treatments in 3 days, were associated with 30-day mortality." (PMID 39564105, 2024). "The VIF of the variables in the model was calculated and the results were all below 2 (albumin: 1.166, APSIII: 1.705, chemotherapy: 1.107, chloride: 1.080, hepatic metastases: 1.084, lactate: 1.129, respiratory failure: 1.079, SAPSII: 1.733, total protein: 1.181), showing no multicollinearity." (PMID 38546896, 2024).